BRAF (B-Raf proto-oncogene, serine/threonine kinase)
Diseases named in the same sentence as BRAF in open-access papers (continued):
Sharing a sentence is not in itself a finding about the gene and the disease.
tumor (continued). "Recent studies have documented localization of some tumor-related genes, such as CDK6, BRAF, and c-MET at the upstream/downstream domain of miR-183-96-182 cluster, suggesting that these genes might be regulated to process similar functions of tumor-related molecules." (PMID 27081087, 2016). "Here, we evaluated the anti-tumor effects of barasertib-HQPA in MM cell models carrying BRAF(V600E) or BRAF(V600K) mutations and wild type BRAF in order to evaluate the efficacy of barasertib in cells responding to anti-BRAF vemurafenib and do not, respectively." (PMID 25623468, 2015). "One patient with a BRAF-negative largest tumor and a BRAF-positive second-largest tumor did have positive radioactive iodine uptake in the mediastinum after surgery, but it was unclear whether this represented ectopic thyroid tissue or recurrent disease and the area was not amenable to biopsy." (PMID 26448939, 2015). "First, because our study lacked data on tumor CIMP (Cpg Island Methylator Phenotype) status and cause of dMMR status, we could not distinguish the correlations of somatic and germline mismatch repair mutations with KRAS and BRAF mutations." (PMID 25929517, 2015). "Of those cases in which molecular analysis of cytology specimens revealed a BRAF mutation, 2/14 (14%) proved benign on histology, while 12/14 (86%) were malignant neoplasms: 11/12 (92%) PTC and 1/12 (8%) PTC follicular variant; no follicular or medullar neoplasms were found." (PMID 26693224, 2015). "However, in that study, while confirming the association between expanding tumor growth, tumor-infiltrating lymphocytes, and loss of MMR protein expression, there was no such association between the presence of KRAS/BRAF mutations and a certain growth pattern or budding intensity in CRC." (PMID 26106602, 2015). "In addition, mutations such as those in KRAS and BRAF that occur early in the development of SBT/LGSC may not be required and/or advantageous for tumor maintenance once additional alterations are acquired." (PMID 25523272, 2014). "Finally, the therapeutic relevance of BRAF mutations in LCH has not been clarified and may differ between tumor types." (PMID 24938183, 2014). "Although, both oncoproteins, BRAF V600E and RET/PTC1, share common property of signaling via activation of MEK-ERK kinase pathway, they have unique phenotypic features, signifying that the different tumor biology may characterize cancers arising from different oncogenes." (PMID 24797369, 2014). "The essential finding of this study was that high ex vivo phosphorylation of PI3K-related substrates by the primary tumor, rather than the KRAS/BRAF mutation status, may be a hallmark of poor metastasis-free survival in LARC patients after radical treatment of the pelvic cavity." (PMID 23226389, 2012). "Finally, the touchdown PCR and melting conditions of this DPYD HRM assay were suitable for analysis of KRAS, BRAF, and EGFR somatic hotspot mutations in tumor samples (not shown), thus enabling simultaneous analysis of relevant mutations for targeted cancer therapy." (PMID 23335937, 2012). "In a hypothesis-generating retrospective analysis of tumour biopsy samples of 113 patients treated with anti-EGFR moAb plus chemotherapy, BRAF-mutated patients did not respond to therapy and had a shorter progession-free survival and overall survival (OS) compared with BRAF wild-type patients." (PMID 20234366, 2010). "Finally, and importantly, not all patients with BRAF+ tumours had BRAF+ cfDNA." (PMID 19861964, 2009). "Immunhistochemically, tumor cells were positive for glial fibrillary acidic protein (GFAP), CD34 V600E-mutant BRAF, and CD34, negative for R132H-mutant IDH1." (PMID 41340779, 2026). "Demographic parameters, tumour characteristics, whether primary or recurrent before new therapy, therapy characteristics such as length and time till the second course of adjuvant treatment, and AE, whether any or drug related, showed no significance comparing PD‐1 and BRAF + MEK‐treated patients." (PMID 40331873, 2025).
tumor (continued). "Furthermore, combining BRAF inhibitors with MEK inhibitors or other immunomodulatory agents could enhance the effectiveness of immunological therapies by preventing MAPK pathway feedback activation and promoting T-cell infiltration into the tumor microenvironment." (PMID 41255582, 2025). "Molecular variants and fusions, often categorized as BRAF-like, RAS-like, and non-BRAF-non-RAS-like, can provide prognostic and tumor behavior information over a population." (PMID 40741176, 2025). "The response to Hsp90 inhibitors in tumours that have already developed drug resistance after treatment with MAPK and/or BRAF inhibitors has not been thoroughly explored." (PMID 40135438, 2025). "Additionally, although the combined inhibition of BRAF, MEK, and CDK4/6 has shown promising anti-tumor effects, flow cytometry analysis has indicated that the massive infiltration of tumor-infiltrating myeloid cells may have an adverse impact on anti-tumor immunity in melanoma." (PMID 41463246, 2025). "Due to tumor-agnostic approvals for patients with BRAFV600E, understanding the frequency and impact of BRAF alterations across non-CRC GI cancers is essential for clinical decision-making." (PMID 40163685, 2025). "Moreover, low tumor mitotic activity was associated with better prognosis in LUAD subgroups with EGFR mutations or pan-negative (no oncogenic alteration in genes including KRAS, EGFR, BRAF, ERBB2, PIK3CA, ALK, and ROS1) but not in those with KRAS or BRAF mutations." (PMID 41404730, 2025). "While BRAF-MEK inhibition is not a solution for all PCPs, this targeted therapy suggests a reliable adjuvant therapy for tumor regression that avoids the surrounding tissue damage characteristic of current treatment approaches." (PMID 40042714, 2025). "Compared with BRAF mice (median onset, 24 days), naevus formation in BRAF PREX2 mice was delayed (median onset, 37 days), with no impact on tumor initiation (median, 301 vs. 407 days), or overall survival (median, 375 vs. 466 days)." (PMID 39636745, 2025). "Upon BRAF-negative status by routine analysis, formalin-fixed paraffin-embedded (FFPE) tumor tissue material was screened by targeted open-end RNA sequencing, which captured the novel in-frame fusion." (PMID 39326005, 2025). "Although the detailed mechanisms of BRAF and APC loss and GNAS expression in this study are not fully understood, shifts in these important signaling pathways involved in tumorigenesis may contribute to changes in the tumor environment and could be associated with the ICI response." (PMID 39796090, 2024). "Universal MMR deficiency (dMMR) screening by immunohistochemistry (IHC) for MMR and BRAF V600E proteins in resected tumor samples revealed significant downregulation of the MLH1 and PMS2 proteins, indicating dMMR, while BRAF V600E was negative." (PMID 38485918, 2024). "Secondly, the SEER database failed to provide possibly crucial data such as tumor marker CEA, microsatellite stability, BRAF, specific chemotherapy drugs, and specific radiotherapy dosage." (PMID 38558258, 2024). "Overall, a recommendation on the frequency of molecular testing of BRAF and NRAS status can be approximated to include at least two metastases, if not all metastases that arise over the course of tumour progression." (PMID 38127894, 2024). "Without UVB irradiation, a tumor was found in 5% (1/20) of the MB mice, which was significantly lower compared with MBU mice albeit indicative of a modest supportive effect of BRAF inhibition on virus-induced tumorigenesis." (PMID 39335105, 2024).
tumor (continued). "This is probably due to a lack of standard testing before BRAF/MEK inhibition became approved, and the fact that PD-1 inhibition is given to patients independently of its expression in tumor tissue." (PMID 38254742, 2024). "Neither BRAF nor NRAS showed any statistically significant correlation between VAF and tumor cellularity." (PMID 38397405, 2024). "Importantly, AP2 gene expression lacked any strong association with cancer staging in BRAF mutated RAI-treated PTC, suggesting that the predictive value was likely related to a poorer response to RAI therapy, in addition to any potential impact on tumour aggressive features." (PMID 37921808, 2024). "Still, to our knowledge, our study is the largest so far and also supports the significance of tumour necrosis independent of many parameters currently evaluated in clinical practice such as lymphovascular invasion, tumour grade, MMR status, and BRAF status." (PMID 37031328, 2023). "Conversely, MYC and MYCN genes display very low correlation and show only a very modest induction in the BRAF- (vs RAS-like) tumour subgroup and are not differentially expressed in tumours vs healthy samples’ comparison." (PMID 37198319, 2023). "Nevertheless, we observed the sequential use of anti‐PD‐1 antibody, after 2 weeks of BRAF/VEGFA targeting, failed to improve tumor control and the tumors rapidly relapsed." (PMID 37183363, 2023). "In IHC, the tumor cells were positive for TTF-1 and thyroglobulin, but negative for CK19, HBME-1, Galectin-1 and BRAF (V600E)." (PMID 37544981, 2023). "Because the included trials did not provide data on tumor location, race, and RAS/BRAF expression, we were not able to analyze the relationship between these factors and the efficacy and safety of aflibercept." (PMID 37657052, 2023). "BRAFV600E has been widely found in various types of neoplasms, including PTC, and its negative impact on BRAF kinase and the MAPK/ERK pathway is well-known." (PMID 37692064, 2023). "Therefore, one could hypothesize that first-line adjuvant treatment preference is rather based on specific patient preferences and less on tumor characteristics, without a difference in the outcome of patients treated with adjuvant BRAF/MEK-inhibition versus anti-PD-1 treatment." (PMID 36672358, 2023). "Moreover, despite the well-known association between BRAF mutations and the presence of MSI in sporadic CRCs (40–60% of CRCs and 3–5% of mCRCs), it is not clear whether tumor-intrinsic factors and the microenvironment are potential targets for ICIs in at least a subset of these patients." (PMID 36010943, 2022). "Eligible patients had recorded programmed death-ligand 1 (PD-L1) tumor proportion score (TPS) and no known actionable EGFR/ALK/ROS1/BRAF genomic alteration." (PMID 35740512, 2022). "Fusions in NTRK genes are more commonly detected in non-Lynch syndrome/MSI-H tumours as well as in wild-type BRAF, KRAS, and NRAS tumours." (PMID 35207616, 2022). "In their treatment algorithm, Stage IVB and IVC ATCs receive neoadjuvant BRAF and MEK inhibitors with or without immunotherapy, and surgery is performed if the tumor is considered to be resectable." (PMID 36052510, 2022). "BRAF-wildtype MAPK-A tumors C14, C20 and C39, and an additional AB-like tumor not studied by RNAseq (C15), appeared on the periphery of the PXA methylation cluster." (PMID 35440587, 2022). "The combination of dabrafenib (BRAF inhibitor) and trametinib (MEK inhibitor) has recently received FDA approval for any BRAF mutant tumor, regardless of the origin site." (PMID 36358751, 2022). "Results revealed HPSE expression to be a prognostic factor of BRAF V600E-mutant CRC, independent of gender, age, primary location, tumor stage, and MMR status." (PMID 36130926, 2022). "It has been demonstrated that the expression of biomarkers such as KRAS, NRAS, and BRAF, in conjunction with the MSI state of the tumour, serves as a negative predictor for anti-EGFR therapy in mCRC patients." (PMID 36612217, 2022).
tumor (continued). "Constitutive RAS activation in NRAS-mutant CMs, and alternative splicing of BRAF V600E in the absence of RAS activity, promote RAF dimerization, which drives tumor progression and resistance to BRAFi." (PMID 35513054, 2022). "The last limitation is the lack of tumor biological data for rat sarcoma viral oncogene homology (RAS) and v-raf murine sarcoma viral oncogene homolog B (BRAF)." (PMID 36612119, 2022). "Among all tested parameters correlated with PFS, gender, age, tumor location, tumor grade, stage, and KRAS as well as BRAF status did not affect PFS or OS by using a Cox regression model." (PMID 35185898, 2022). "Overall, our results indicate that DEL-22379 effectively suppresses tumor growth of ATC-derived cell lines and impairs metastatic dissemination, especially in BRAF-mutant cells, and with no apparent signs of toxicity." (PMID 36056964, 2022). "During vaccination period, 16 (26.7%) patients received ICI therapy, 10 (16.7%) patients TT (BRAF inhibitors and MEK inhibitors), 1 chemotherapy, and 33 (55.0%) had no ongoing tumor therapy (NTT)." (PMID 35609553, 2022). "However, the existing subtyping of thyroid cancer revolves around BRAF mutations and RAS mutations, which could not fully cover the molecular and clinical characteristics of PTC, without considering other genomic changes and the tumor microenvironment." (PMID 36253446, 2022). "LN1 had BRAF fusion but LN2 did not, and there was a significant difference in tumor cell clones between LN1 and LN2." (PMID 36923281, 2022). "In the pacritinib-treated tumor, no changes in pMEK, total ERK, and BRAF were observed; however, pERK was downregulated and NF1 was significantly upregulated, likely reflecting pathway crosstalk." (PMID 35835937, 2022). "Studies have shown that in the receptor tyrosine kinase (RTK)-RAS pathway, irrespective of tumor types, Kirsten rat sarcoma (KRAS) is the most frequently altered gene, followed by BRAF, and EGFR41." (PMID 36276638, 2022). "Because of faint labelling of tumor cells, the discordant sample—VE1 IHC negative and BRAF V600E/E2/D Idylla positive—was tested again with BRAF VE1 IHC using a red chromogen (UltraView Universal Alkaline Phosphatase Red Detection Kit, Roche)." (PMID 35328303, 2022). "Resistance to BRAF/MEK inhibitors is generated by genetic and non-genetic factors inherent to a tumor or acquired during therapy." (PMID 35565444, 2022). "By using PDOs as a model system for evaluating clinically relevant drug responses, we conclude that KRAS and BRAF, but not MMR status, are dominant factors in determining the intrinsic sensitivity of tumor cells to chemotherapy and targeted therapy." (PMID 34771595, 2021). "Eight patients received re-challenge therapy with BRAF with or without MEK inhibitors; one achieved PR and six had tumor shrinkage, of whom three were alive until the last follow-up (median PPS of 40.4 months)." (PMID 34504796, 2021). "YAP silencing is able to enhance sensitivity to vemurafenib (a BRAF inhibitor) and trametinib (a MEK inhibitor) in a variety of tumor cells carrying the BRAF V600E mutant, without affecting vehicle-treated tumors." (PMID 33467099, 2021). "This patient was not excluded by the tumour sequencing pipeline as MLH1 promoter methylation was not tested, and the tumour was BRAF c.1799T>A (p.V600E) negative." (PMID 33499123, 2021). "Another option is the use of agents that do not target the BRAF, NRAS, or MEK/ERK pathway at all, but inhibit essential mechanisms (such as antiapoptosis) important for tumor growth." (PMID 34063141, 2021). "Both drugs affected the viability of mut-BRAF, but not wt-BRAF, CRC cells, and when used in combination they triggered massive apoptosis in in vitro models and significant tumor reduction in xenograft models." (PMID 34065438, 2021). "Third is the lack of information on perioperative treatment or molecular tumor characteristics, such as the data on the RAS, BRAF, and MSI status, and serum CEA levels." (PMID 34208938, 2021).
tumor (continued). "Despite the fact that BRAF is a key effector downstream of RAS and upstream of MEK, ATP-competitive BRAFi are not effective in RAS mutant tumor models." (PMID 33042833, 2020). "Additional genetic testing revealed the patient was negative for ALK fluorescence in situ hybridization, ROS1, BRAF, and EGFR and PD-L1 22C3 IHC with Tumor Proportion Score (TPS) of <1%." (PMID 33101670, 2020). "Second, the SEER database did not collect data on the tumor recurrence, RAS, BRAF status, and post-operative complications." (PMID 33195291, 2020). "No relation between SCC tumor grade of SCC and the expression of BRAF V600E was identified (P=0.152)." (PMID 31531096, 2019). "Genetic profiling of bulk tissues confirmed that all tumors contained BRAF alterations, including five tumors with the classic KIAA1549-BRAF 16:9 translocation and one tumor with a noncanonical BRAF duplication event." (PMID 31427603, 2019). "Although the MCL-1 inhibitor alone did not affect tumor growth, sequential BRAF and MCL-1 inhibition led to profound tumor regression." (PMID 31727958, 2019). "The tumor was positive for OLIG2 and GFAP and negative for BRAF V600E and IDH1 R132H mutant protein immunostains." (PMID 29141672, 2017). "In reality, the REB array can be used to exclude tumours with common BRAF or NRAS mutations from further testing, allowing resources to be concentrated on sequencing cases where the driver mutation is not known, and knowledge of the KIT status of the tumour may be helpful." (PMID 28228113, 2017). "The tumor demonstrated extensive immunostaining with GFAP and OLIG2 (not shown), and was negative for BRAF V600E and for IDH1 R132H mutant protein." (PMID 29141672, 2017). "More recently it was demonstrated that the cMET clinical score was not a statistically significant predictive factor for therapy with BRAF-inhibitor, and stromal or parenchymal HGF expression levels did not indicate tumor response to inhibitors of BRAF." (PMID 28829835, 2017). "CIN in sporadic CRC in conjunction with APC gene mutation results in microsatellite stable (MSS), CIMP negative and BRAF, KRAS wild type tumours." (PMID 28067827, 2017). "While the PTEN loss is also reported in COSMIC for COLO829, no copy number changes were identified to impact the BRAF, or CDKN2A, loci for the COLO829 tumor in COSMIC22." (PMID 27094764, 2016). "Similar results were obtained when tumours were treated with digoxin rather than digitoxin or when the MAPK pathway was inhibited with BRAF inhibitor (vemurafenib) rather than MEK inhibitor." (PMID 27545456, 2016). "While BRAF-i had no substantial effect, MEK-i sharply reduced tumor cell lysis mediated by IL-2- and IL-15-activated NK cells." (PMID 27563819, 2016). "This indicates that the individual MMP/TIMP composition at the leading edge of each tumor might create a fine-tuned microenvironment irrespective of (and of higher prognostic relevance than) expression of one MMP or baseline oncogenic mutations, such as KRAS or BRAF." (PMID 26106602, 2015). "Only two tumors (both BRAF wildtype) had detectable levels of FOXB2 expression, and an additional three samples showed no detectable FOXB2 expression in either tumor or normal tissue." (PMID 23324568, 2013). "Unlike BRAF genotypes, KIT genotypes were poorly matched between primary tumours, metastases, and CTC." (PMID 22281663, 2012). "Therefore, we supplemented MSI analyses with the BRAF mutation and methylation analyses of MMR genes, and used a combination of these three molecular tests to discriminate colorectal tumours that are likely to be associated with LS from tumours that are not likely to be associated with LS." (PMID 20051945, 2010).